MCRIP1 (MAPK regulated corepressor interacting protein 1)
Description:
The phosphorylation status of MCRIP1 functions as a molecular switch to regulate epithelial-mesenchymal transition. Unphosphorylated MCRIP1 binds to and inhibits the transcriptional corepressor CTBP(s). When phosphorylated by MAPK/ERK, MCRIP1 releases CTBP(s) resulting in transcriptional silencing of the E-cadherin gene and induction of epithelial-mesenchymal transition.
Synonyms: FAM195B; GRAN2; MCRIP
Tractability: PROTAC: ubiquitination databases record sites on it.
Gene: Protein-coding gene on chromosome 17 (81,821,790 to 81,833,302, reverse strand). Ensembl gene ENSG00000225663.
Subcellular location: Nucleus; Cytoplasm, Stress granule
Subcellular location (Human Protein Atlas): Cytosol
Pathways (Reactome):
Cell-Cell communication: Negative Regulation of CDH1 Gene Transcription
Gene Ontology:
Molecular function: protein binding
Biological process: regulation of epithelial to mesenchymal transition
Cellular component: cytoplasm; cytoplasmic stress granule; nucleus; nucleoplasm
Genetic constraint (gnomAD): Loss-of-function variants: 10 observed, 13.92 expected, observed/expected ratio (o/e) 0.72, 90% interval 0.44 to 1.22. The upper end of that interval is the gene's LOEUF score, 1.22, which puts it in group 5 of 6, group 1 being the genes least tolerant of losing a copy. Missense variants: 119 observed, 131.57 expected, observed/expected ratio (o/e) 0.9, 90% interval 0.78 to 1.05. Synonymous variants: 53 observed, 54.91 expected, observed/expected ratio (o/e) 0.97, 90% interval 0.77 to 1.21.
Homologues: Orthologues: pig MCRIP1 (94% identical), dog MCRIP1 (91% identical), guinea pig MCRIP1 (91% identical), mouse Mcrip1 (91% identical), rat Mcrip1 (89% identical), chimpanzee MCRIP1 (78% identical), tropical clawed frog mcrip1 (76% identical), zebrafish mcrip1 (59% identical). Paralogues in human: MCRIP2 (43% identical), FGFRL1 (23% identical).
Diseases named in the same sentence as MCRIP1 in open-access papers:
MCRIP1 is named in the same sentence as 3 diseases in open-access papers, as found by Europe PMC text mining. Sharing a sentence is not in itself a finding about the gene and the disease. The quoted sentences say what the papers report.
respiratory failure (1 paper, 2019). The significant impairment of gas exchange within the lungs resulting in hypoxia, hypercarbia, or both, to the extent that organ tissue perfusion is severely compromised. "The majority of Mcrip1−/− mice died in the neonatal stage owing to respiratory failure caused by deflation of alveolar sacs." (PMID 31240265, 2019). "In Mcrip1−/− neonates, the lungs were relatively deflated and the alveolar sac space was smaller than that of wild-type lungs, suggesting that the observed respiratory failure was caused by impaired inflation of alveoli." (PMID 31240265, 2019). "The Mcrip1-KO mice died shortly after birth owing to respiratory failure that resembles human infant respiratory distress syndrome (RDS)." (PMID 31240265, 2019). "Thus, MCRIP1 depletion elicits abnormal epigenetic silencing of these surfactant protein genes, resulting in fatal respiratory failure at birth, which resembles human RDS." (PMID 31240265, 2019). "We found that most of the Mcrip1−/− newborn pups exhibited gasping breath, tachypnea and cyanosis, and died within 12 hours after birth, suggesting that the observed lethality resulted from respiratory failure." (PMID 31240265, 2019).
respiratory disease (1 paper, 2019). "They show that MCRIP1 deficiency in mice causes fatal neonatal respiratory disease by inducing epigenetic silencing of SP-B/C." (PMID 31240265, 2019). "Further investigation is required to clarify the role of MCRIP1 in the etiology of neonatal respiratory diseases." (PMID 31240265, 2019).
MCRIP1 also shares sentences with these, for which no sentence is quoted: tumor (1 paper).